ZNF319 (zinc finger protein 319)
Description:
May be involved in transcriptional regulation.
Synonyms: KIAA1388; Zfp319
Tractability: PROTAC: UniProt records ubiquitination sites on it; ubiquitination databases record sites on it; its protein half-life has been measured.
Gene: Protein-coding gene on chromosome 16 (57,994,673 to 58,000,672, reverse strand). Ensembl gene ENSG00000166188.
Subcellular location: Nucleus
Subcellular location (Human Protein Atlas): Nucleoplasm
Gene Ontology:
Molecular function: protein binding; transcription cis-regulatory region binding
Biological process: regulation of transcription by RNA polymerase II; regulation of gene expression
Cellular component: nucleus
Genetic constraint (gnomAD): Loss-of-function variants: 15 observed, 38.32 expected, observed/expected ratio (o/e) 0.39, 90% interval 0.26 to 0.6. The upper end of that interval is the gene's LOEUF score, 0.6, which puts it in group 2 of 6, group 1 being the genes least tolerant of losing a copy. Missense variants: 635 observed, 797 expected, observed/expected ratio (o/e) 0.8, 90% interval 0.75 to 0.85. Synonymous variants: 368 observed, 359.54 expected, observed/expected ratio (o/e) 1.02, 90% interval 0.94 to 1.12.
Homologues: Orthologues: chimpanzee ZNF319 (100% identical), pig ZNF319 (98% identical), dog ZNF319 (98% identical), rat Zfp319 (97% identical), guinea pig ZNF319 (97% identical), mouse Zfp319 (96% identical), rabbit ZNF319 (84% identical), tropical clawed frog znf319 (72% identical), zebrafish znf319b (68% identical). Paralogues in human: ZNF646 (23% identical), ZNF407 (19% identical), ZNF287 (18% identical), ZNF572 (17% identical), ZNF697 (17% identical), ZNF774 (17% identical), ZKSCAN7 (16% identical), ZNF17 (16% identical), ZNF285 (16% identical), ZNF34 (16% identical), ZBTB17 (16% identical), ZNF398 (16% identical), and 38 more.
Diseases named in the same sentence as ZNF319 in open-access papers:
ZNF319 is named in the same sentence as 4 diseases in open-access papers, as found by Europe PMC text mining. Sharing a sentence is not in itself a finding about the gene and the disease. The quoted sentences say what the papers report.
breast carcinoma (3 papers, 2023). "Remarkably, in almost all subtypes of breast cancer, high expression of ZNF319 is associated with better clinical prognosis." (PMID 37664112, 2023). "Following this, a transcriptomic study on breast cancer cells with CRISPR/Cas9 deleted ZNF 319 identified ZNF319 as a tumor suppressor gene, that reduces the proliferation in breast cancer and therefore is involved in various potential signaling mechanisms and other biological functions." (PMID 37469704, 2023). "After performing a genome-wide CRISPR/Cas9 KO screen in an orthotopic breast cancer MCF7 xenograft, they found that ZNF319 could be implicated in the regulation of breast cancer progression." (PMID 37686639, 2023). "ZNF319, a member of the Zinc Finger Protein (ZNF) family, exhibits low expression in tumor tissues of breast cancer patients." (PMID 37664112, 2023).
diabetes (1 paper, 2019). "Several other genes displaying inverted correlations have previously been linked to diabetes (7/18), either by functional studies (TRIB1, glucose metabolism; NFKBIA, insulin resistance pathway) or as candidate disease genes in GWAS or gene expression studies (TMPPE, PRTG, and ZNF319)." (PMID 31159854, 2019).
ZNF319 also shares sentences with these, for which no sentence is quoted: colon cancers (1 paper); tumor (1).